XPC (XPC complex subunit, DNA damage recognition and repair factor)
Description:
Involved in global genome nucleotide excision repair (GG-NER) by acting as damage sensing and DNA-binding factor component of the XPC complex. Has only a low DNA repair activity by itself which is stimulated by RAD23B and RAD23A. Has a preference to bind DNA containing a short single-stranded segment but not to damaged oligonucleotides. This feature is proposed to be related to a dynamic sensor function: XPC can rapidly screen duplex DNA for non-hydrogen-bonded bases by forming a transient nucleoprotein intermediate complex which matures into a stable recognition complex through an intrinsic single-stranded DNA-binding activity. The XPC complex is proposed to represent the first factor bound at the sites of DNA damage and together with other core recognition factors, XPA, RPA and the TFIIH complex, is part of the pre-incision (or initial recognition) complex. The XPC complex recognizes a wide spectrum of damaged DNA characterized by distortions of the DNA helix such as single-stranded loops, mismatched bubbles or single-stranded overhangs. The orientation of XPC complex binding appears to be crucial for inducing a productive NER. XPC complex is proposed to recognize and to interact with unpaired bases on the undamaged DNA strand which is followed by recruitment of the TFIIH complex and subsequent scanning for lesions in the opposite strand in a 5'-to-3' direction by the NER machinery. Cyclobutane pyrimidine dimers (CPDs) which are formed upon UV-induced DNA damage esacpe detection by the XPC complex due to a low degree of structural perurbation. Instead they are detected by the UV-DDB complex which in turn recruits and cooperates with the XPC complex in the respective DNA repair. In vitro, the XPC:RAD23B dimer is sufficient to initiate NER; it preferentially binds to cisplatin and UV-damaged double-stranded DNA and also binds to a variety of chemically and structurally diverse DNA adducts. XPC:RAD23B contacts DNA both 5' and 3' of a cisplatin lesion with a preference for the 5' side. XPC:RAD23B induces a bend in DNA upon binding. XPC:RAD23B stimulates the activity of DNA glycosylases TDG and SMUG1. In absence of DNA repair, the XPC complex also acts as a transcription coactivator: XPC interacts with the DNA-binding transcription factor E2F1 at a subset of promoters to recruit KAT2A and histone acetyltransferase complexes (HAT). KAT2A recruitment specifically promotes acetylation of histone variant H2A.Z.1/H2A.Z, but not H2A.Z.2/H2A.V, thereby promoting expression of target genes.
Synonyms: XPCC; RAD4; XP3; p125
Tractability: Small molecule: a structure with a bound ligand is known. Antibody: its Gene Ontology location is reachable by antibodies, with high confidence; the Human Protein Atlas places it where antibodies can reach. PROTAC: UniProt records ubiquitination sites on it; ubiquitination databases record sites on it; its protein half-life has been measured.
Safety:
Unwanted effects reported when the protein is acted on. In parentheses: how it was acted on, where the effect was seen, and who reports it.
drug toxicity (source: ClinPGx)
GI toxicity (source: ClinPGx)
hematologic toxicity (source: ClinPGx)
hematologic toxicity, leukopenia, and GI toxicity (source: ClinPGx)
infection (source: ClinPGx)
leukopenia (source: ClinPGx)
neutropenia (source: ClinPGx)
ototoxicity (source: ClinPGx)
Gene: Protein-coding gene on chromosome 3 (14,145,145 to 14,178,652, reverse strand). Ensembl gene ENSG00000154767.
Subcellular location: Nucleus; Chromosome; Cytoplasm
Subcellular location (Human Protein Atlas): Nucleoplasm; Plasma membrane
Pathways (Reactome):
DNA Repair: DNA Damage Recognition in GG-NER; Formation of Incision Complex in GG-NER
Metabolism of proteins: SUMOylation of DNA damage response and repair proteins
Gene Ontology:
Molecular function: damaged DNA binding; DNA damage sensor activity; protein binding; protein-containing complex binding; single-stranded DNA binding; transcription coactivator activity; bubble DNA binding; heteroduplex DNA loop binding; DNA binding; RNA polymerase II-specific DNA-binding transcription factor binding
Biological process: nucleotide-excision repair; positive regulation of DNA-templated transcription; regulation of mitotic cell cycle phase transition; UV-damage excision repair; DNA repair; mismatch repair; regulation of cell cycle phase transition; regulation of mitotic cell cycle; response to auditory stimulus; response to xenobiotic stimulus
Cellular component: chromosome; cytoplasm; nucleoplasm; nucleotide-excision repair complex; nucleus; plasma membrane; XPC complex; chromatin; site of DNA damage
Genetic constraint (gnomAD): Loss-of-function variants: 71 observed, 84.53 expected, observed/expected ratio (o/e) 0.84, 90% interval 0.69 to 1.02. The upper end of that interval is the gene's LOEUF score, 1.02, which puts it in group 4 of 6, group 1 being the genes least tolerant of losing a copy. Missense variants: 1,034 observed, 1,075.8 expected, observed/expected ratio (o/e) 0.96, 90% interval 0.91 to 1.01. Synonymous variants: 394 observed, 400.12 expected, observed/expected ratio (o/e) 0.98, 90% interval 0.91 to 1.07.
Gene-disease validity (ClinGen):
ClinGen rates the evidence that XPC causes each of these diseases.
xeroderma pigmentosum group C (autosomal recessive): Definitive.
Homologues: Orthologues: chimpanzee XPC (99% identical), macaque XPC (96% identical), dog XPC (78% identical), rabbit XPC (78% identical), rat Xpc (75% identical), mouse Xpc (74% identical), guinea pig XPC (73% identical), pig XPC (71% identical), tropical clawed frog xpc (54% identical), zebrafish xpc (43% identical), Drosophila melanogaster Xpc (31% identical), Caenorhabditis elegans xpc-1 (26% identical).
Diseases named in the same sentence as XPC in open-access papers:
XPC is named in the same sentence as 125 diseases in open-access papers, as found by Europe PMC text mining. Sharing a sentence is not in itself a finding about the gene and the disease. The quoted sentences say what the papers report.
xeroderma pigmentosum (59 papers, 2008 to 2025). Xeroderma pigmentosum (XP) is a rare genodermatosis characterized by extreme sensitivity to ultraviolet (UV)-induced changes in the skin and eyes, and multiple skin cancers. "In this study, we established and characterized novel iPSC lines from a patient with Xeroderma Pigmentosum group C (XP-C), harboring a homozygous loss-of-function mutation in the XPC gene (c.1830C>A, p.Tyr610*)." (PMID 41440007, 2025). "Rare germline variants in ERCC3, XPA, and XPC are related to xeroderma pigmentosum, a disease that increases the appearance of ultraviolet-induced skin cancer at an early age." (PMID 39408606, 2024). "XPC deficiency was first discovered to play a critical role in the development of xeroderma pigmentosum, a condition characterized by early and aggressive melanomatous and non-melanomatous skin cancers, including squamous cell cancers of the skin." (PMID 38672576, 2024). "A 17-year-old female Korean patient (XP115KO) was previously diagnosed with Xeroderma pigmentosum group C (XPC) by Direct Sanger sequencing, which revealed a homozygous nonsense mutation in the XPC gene (rs121965088: c.1735C > T, p.Arg579Ter)." (PMID 37109656, 2023). "In particular, they possess an N-terminal ubiquitin-like domain (UBL), a central ubiquitin-associated domain (UBA1), followed by a RAD4/XPC (xeroderma pigmentosum group C) binding domain (RBD/XPCB) and a C-terminal ubiquitin-associated domain (UBA2)." (PMID 34824204, 2021). "This was the case for the recurrent mutation p.V548AfsX25 affecting XPC and leading to Xeroderma pigmentosum." (PMID 33679882, 2021). "Mutations in the nucleotide excision repair gene XPC are causal of the autosomal recessive disease Xeroderma pigmentosum." (PMID 33227964, 2020). "In this case study, we report a novel protein truncating mutation in XPC associated with autosomal recessive xeroderma pigmentosum in a consanguineous Pakistani family." (PMID 31923348, 2020). "Individuals with xeroderma pigmentosum syndrome are deficient in the core NER genes, such as DDB2 and XPC (xeroderma pigmentosum complementation group E and C, respectively), and are susceptible to the development of skin cancer." (PMID 32722430, 2020). "Mutations in XPC can result in a rare autosomal recessive disorder termed Xeroderma pigmentosum, which is characterized by increased sensitivity to sunlight and the development of carcinomas at an early age." (PMID 31572446, 2019). "Mutations in XPC that impair the production of the XPC protein are related to Xeroderma Pigmentosum (XP), a rare recessive disorder, which makes patients extremely sensitive to ultraviolet light." (PMID 31382494, 2019). "XPC is involved in DNA damage repair and is associated with disease characterized by an extreme sensitivity to ultraviolet rays from sunlight, such as xeroderma pigmentosum, complementation group c and xeroderma pigmentosum, variant type, and the deletion of XPC leads to lung tumors in mice." (PMID 33657282, 2021). "The XPC protein, which is mutated in xeroderma pigmentosum (XP) complementation group C (XP-C), is a lesion recognition factor in NER, but it has also been shown to interact with and stimulate DNA glycosylases, to act as transcriptional co-activator and on energy metabolism adaptation." (PMID 32639509, 2020). "In addition to the well-characterised NER deficient skin cancer disorder xeroderma pigmentosum, the relationship between XPC deficiency and carcinogenesis after UV radiation has been described for melanoma and squamous cell carcinomas." (PMID 27487145, 2016). "The role of the XPC gene in carcinogenesis started to attract attention because of the observation that mutations in the DNA repair genes can cause the inherited disease xeroderma pigmentosum (XP)." (PMID 27669310, 2016).
xeroderma pigmentosum (continued). "The clinical feature of a mutated XPC gene in xeroderma pigmentosum (hypersensitivity to UV radiation and skin cancer) highlights the extraordinary importance of this repair-initiating function for the excision of photodimers (CPDs and 6-4PPs) induced by sunlight exposure." (PMID 26521083, 2016). "XPC is mutated in xeroderma pigmentosum and functions in nucleotide excision repair." (PMID 25845598, 2015). "TTD is a distinct condition from Xeroderma Pigmentosum (XP) caused by mutation in eight XP‐associated genes: XPA, XPD (ERCC2), XPB (ERCC3), XPF (ERCC4), XPG (ERCC5), XPC, XPE (DDB2), and a variant form related to the POLH gene." (PMID 39976384, 2025). "The XPC and CSB genes were mutated in cell lines derived from Xeroderma Pigmentosum patients as well as from normal human fibroblasts and repair was analyzed at the whole genome level using the very sensitive XR-seq method." (PMID 37144462, 2023). "We were unable to detect a change in the level of the key DNA repair protein, xeroderma pigmentosum, complementation group C, also known as XPC, by western blotting in UV‐exposed keratinocytes treated with NPS‐2143 (data not shown)." (PMID 35288938, 2022). "Initiated by the xeroderma pigmentosum group C (XPC) complex, GG-NER recognizes helix-distorting lesions anywhere throughout the genome but is primarily responsible for the slower repair of damage on non-transcribed portions." (PMID 35530314, 2022). "Compared to the DON group and the HO-1shRNA group, the expression of excision repair cross-complementation group 1 (ERCC1) and xeroderma pigmentosum complementation group C (XPC) in the mouse liver of the HO-1OE group was much increased." (PMID 34679025, 2021). "BZ16 (a derivative of RTC13) and RTC14 were also shown to increase XPC mRNA expression in skin fibroblasts from xeroderma pigmentosum (Group C) patients." (PMID 26287674, 2015). "The diversity of these roles indicates that XPC is involved in many more cellular processes than previously thought and provides a gateway for further understanding of the effects of xeroderma pigmentosum." (PMID 24366067, 2013). "Understanding the interactome of XPC is crucial in determining the mechanism of DNA damage recognition in the context of chromatin and the pathogenesis of xeroderma pigmentosum." (PMID 24366067, 2013). "In addition, an interesting report demonstrated that, like ultraviolet irradiation, As2O3 induced xeroderma pigmentosum group C (XPC) in U-87 cells, and XPC silencing sensitized the cells to As2O3 via increased oxidative stress." (PMID 39768226, 2024). "In addition, several essential NER genes associated closely with xeroderma pigmentosum (XP) are XPA, XPB, XPC, XPD, XPE, XPF, and XPG, respectively." (PMID 38089451, 2022). "Biallelic pathogenic variants in one of the seven NER genes coding for the so-called complementation groups, XPA, ERCC3, XPC, ERCC2, DDB2, ERCC4, ERCC5, the NER gene ERCC1, and the gene coding for XP variant, POLH, are the causes of the rare hereditary disease Xeroderma pigmentosum (XP)." (PMID 35174087, 2022). "Moreover, ATM and ATR mediate the increase in DDB2 (Damage Specific DNA Binding Protein 2) and XPC (xeroderma pigmentosum, complementation group C)." (PMID 34356109, 2021). "Another primary NER initiating protein is the xeroderma pigmentosum group C (XPC)." (PMID 35056973, 2021). "The reduced NER activity may result from the lack of interaction between key lesion recognizer—damaged DNA-binding protein 2 (DDB2) or xeroderma pigmentosum group C (XPC) and PARP1 in the presence of UV damage affecting damage recognition." (PMID 33019598, 2020). "Xeroderma pigmentosum (XP) is a rare autosomal recessive disorder caused by changes in the DNA repair pathway related to variants in eight genes, and it is clinically recognized as XPA, XPB, XPC, XPD, XPE, XPF, XPG, and XPV." (PMID 32935933, 2020).
xeroderma pigmentosum (continued). "In combination with biochemical reconstitution assays, this method demonstrated that locating bulky lesions depends on a heterotrimeric factor composed of xeroderma pigmentosum group C (XPC;) one of two human RAD23 homologs (predominantly RAD23B;) and centrin 2 (CETN2;)." (PMID 26521083, 2016). "The results of immunoblot analyses showed that xeroderma pigmentosum, complementation group C (XPC), and damage-specific DNA binding protein 2 (DDB2) in the NER pathway could not be induced after MMC treatment." (PMID 27833080, 2016). "Pathogenic mutations in the GGR components XPC and DDB2 (XPE) result in xeroderma pigmentosum (XP) a disease characterised by increased UV-sensitivity and skin cancer incidence." (PMID 26913219, 2015). "These diseases include xeroderma pigmentosum (XP) which is due to a defect in one of approximately eleven XP associated genes (including XPA, ERCC3 (XPB), XPC, and POLH (XPV))." (PMID 23285288, 2012). "GGR is a process which detects DNA sequence damage by XPC proteins (xeroderma pigmentosum complementation group C) and XPE (xeroderma pigmentosum complementation group E)." (PMID 30116756, 2018). "Several xeroderma pigmentosum (XP) group genes are involved in NER, including group C (XPC), group D (ERCC2/XPD) and group G (ERCC5/XPG)." (PMID 27246611, 2016). "Results showed that post-UVB silibinin treatment accelerates DNA repair via activating the NER pathway including the expression of XPA (xeroderma pigmentosum complementation group A), XPB, XPC, and XPG." (PMID 26447614, 2015). "XPC is one of the seven complementation groups of xeroderma pigmentosum (XP)." (PMID 24366067, 2013). "Xeroderma pigmentosum complementation group C (XPC) is one of the essential damage recognition proteins of the GG-NER pathway and its dysfunction results in xeroderma pigmentosum (XP), a disorder involving photosensitivity and a predisposition to cancer." (PMID 24366067, 2013). "Here, no significant changes in the xeroderma pigmentosum group C (XPC) DNA repair protein were observed." (PMID 39902465, 2024). "The deficiency of specific proteins can lead to specific diseases; for example, XPA, XPB, XPC, XPD, XPE, XPF and XPG are derived from xeroderma pigmentosum and belong to the GG-NER sub-pathway, while CSA and CSB proteins are associated with Cockayne syndrome, which belongs to the TC-NER sub-pathway." (PMID 36290563, 2022). "Discovering the proteins that interact with XPC within the cell and, therefore, the cellular functions of XPC in addition to its role in GG-NER, could provide the understanding necessary to comprehend the full effects of xeroderma pigmentosum." (PMID 24366067, 2013). "The XPC, XPD and XPA complementation groups present the most frequent forms of Xeroderma pigmentosum in Europe, North Africa, Japan and the USA, as they are responsible for about 90% of XP patients worldwide." (PMID 29208038, 2017). "However, depletion of HBO1 in cells derived from xeroderma pigmentosum patient complementation groups, XPE, XPC and XPA, did not lead to additional sensitivity towards ultraviolet irradiation." (PMID 28719581, 2017). "We hypothesized that genetic polymorphism in other NER genes, such as XPB (Xeroderma pigmentosum group B), XPC (Xeroderma pigmentosum group C) and XPF (Xeroderma pigmentosum group F), which have not been studied, may be related to an individual’s susceptibility to benzene toxicity." (PMID 26681190, 2015).